BCAS2 (BCAS2 pre-mRNA processing factor)
Description:
Required for pre-mRNA splicing as component of the activated spliceosome. Component of the PRP19-CDC5L complex that forms an integral part of the spliceosome and is required for activating pre-mRNA splicing. May have a scaffolding role in the spliceosome assembly as it contacts all other components of the core complex. The PRP19-CDC5L complex may also play a role in the response to DNA damage (DDR).
Synonyms: DAM1; SPF27; Snt309
Tractability: Small molecule: a structure with a bound ligand is known. PROTAC: ubiquitination databases record sites on it; its protein half-life has been measured.
Gene: Protein-coding gene on chromosome 1 (114,567,552 to 114,581,648, reverse strand). Ensembl gene ENSG00000116752.
Subcellular location: Nucleus; Nucleus, nucleolus
Subcellular location (Human Protein Atlas): Centrosome; Nuclear speckles
Pathways (Reactome):
Disease: Dengue Virus-Host Interactions
Metabolism of RNA: mRNA Splicing - Major Pathway
Gene Ontology:
Molecular function: protein binding
Biological process: mRNA splicing, via spliceosome; RNA splicing; RNA splicing, via transesterification reactions; mRNA processing
Cellular component: DNA replication factor A complex; nuclear speck; nucleus; post-mRNA release spliceosomal complex; post-spliceosomal complex; Prp19 complex; spliceosomal complex; U2-type catalytic step 1 spliceosome; U2-type catalytic step 2 spliceosome; catalytic step 2 spliceosome; nucleoplasm; nucleolus
Genetic constraint (gnomAD): Loss-of-function variants: 23 observed, 21.89 expected, observed/expected ratio (o/e) 1.05, 90% interval 0.75 to 1.49. The upper end of that interval is the gene's LOEUF score, 1.49, which puts it in group 6 of 6, group 1 being the genes least tolerant of losing a copy. Missense variants: 160 observed, 200.2 expected, observed/expected ratio (o/e) 0.8, 90% interval 0.7 to 0.91. Synonymous variants: 60 observed, 73.25 expected, observed/expected ratio (o/e) 0.82, 90% interval 0.66 to 1.02.
Homologues: Orthologues: chimpanzee BCAS2 (100% identical), macaque BCAS2 (100% identical), mouse Bcas2 (100% identical), rabbit BCAS2 (100% identical), rat Bcas2 (99% identical), dog BCAS2 (99% identical), guinea pig BCAS2 (99% identical), pig BCAS2 (98% identical), tropical clawed frog bcas2 (86% identical), zebrafish bcas2 (82% identical), Drosophila melanogaster BCAS2 (55% identical), Caenorhabditis elegans bcas-2 (37% identical).
Diseases named in the same sentence as BCAS2 in open-access papers:
BCAS2 is named in the same sentence as 21 diseases in open-access papers, as found by Europe PMC text mining. Sharing a sentence is not in itself a finding about the gene and the disease. The quoted sentences say what the papers report.
breast carcinoma (14 papers, 2008 to 2025). "The results manifested that full-length CDS sequence of BCAS2 was consisted of 678 bp nucleotides, and encoded a total of 225 amino acids, which is consistent in length with initially study in human breast cancer cell lines." (PMID 37901468, 2023). "Breast cancer amplified sequence 2 (Bcas2), also known as splicing factor 27 (SPF27), is markedly upregulated on the gene expression level in human breast cancer cells." (PMID 40585763, 2025). "Breast carcinoma amplified sequence 2 (BCAS2) is a novel gene proposed by differential display (DD) technique in human breast cancer cell line." (PMID 37901468, 2023). "PRRX2 eRNA and mRNA expression levels are correlated, and targeting the PRRX2 eRNA to its cognate enhancer promotes breast cancer cell proliferation, an effect that is abrogated upon depletion of BCAS2." (PMID 36039999, 2022). "Elevated expression of BCAS2 positively affects proliferation, clonogenicity and migration of breast cancer cells and directly activates ERα regulated genes which have been shown to play a role in tumor growth and progression." (PMID 30813351, 2019). "This supports a role for BCAS2 in the progression of breast cancer, both before and after endocrine resistance sets in." (PMID 30813351, 2019). "In this study, we have reinforced and enhanced our knowledge about the role of BCAS2 as an ERα coactivator and its regulation in breast cancer cells." (PMID 30813351, 2019). "We have shown that BCAS2 is a bona fide coactivator of ERα in breast cancer cell lines, being recruited to target gene promoters and increasing expression of a subset of E2 regulated genes." (PMID 30813351, 2019). "Our data showing that BCAS2 can synergize with these coactivators, as well as promote carcinogenic processes, shows it has important implications in breast cancer." (PMID 30813351, 2019). "This suggests a role for BCAS2 overexpression in promoting ERα activity in a reduced estrogen environment, as is found during hormonal treatment for breast cancer." (PMID 30813351, 2019). "This suggests that BCAS2 is a coactivator that can be shared between steroid hormone receptors and activates important growth modulators in breast cancer cells." (PMID 30813351, 2019). "Luciferase assays, carried out in breast cancer cell lines, confirmed that BCAS2 increases ERα transcriptional activity." (PMID 30813351, 2019). "The enhanced expression of BCAS2 in human mammary cancer cell lines increases their proliferation, migration and colony formation." (PMID 30813351, 2019). "Recent studies also demonstrated the tumor suppressor role of ERRβ through BCAS2 in breast cancer cells." (PMID 29843638, 2018). "Genes such as NCOA3, PPM1D, PSMD6 and BCAS2 were detected with high expression and copy numbers in MCF-7 cells, and these genes have been associated with breast cancer progression." (PMID 18350142, 2008). "It was originally proposed as DNA amplified in mammary carcinoma (DAM1), then named BCAS2." (PMID 37901468, 2023). "Nras and Bcas2 were of particular interest as Ras family members are known to be activated downstream of EGF receptor signaling to regulate various physiological processes including proliferation, and Bcas2 is an oncogene known to positively affect clonogenicity and migration of breast cancer cells." (PMID 35559667, 2022). "Additionally, BCAS2 has been shown to be overexpressed in TAM resistant MCF7 cells and increased expression is associated to shorter relapse-free survival of breast cancer patients." (PMID 30813351, 2019). "This suggests that BCAS2 regulates AF-1 activity on the ERα N-terminus and may play a role in regulating estrogen dependent growth in breast cancer." (PMID 30813351, 2019).
breast carcinoma (continued). "Thus, we would expect that overexpression of BCAS2 can impact the physiologic environment of estrogen dependent breast cancer cells and be involved in carcinogenic processes." (PMID 30813351, 2019). "Therefore, we tested the effect of BCAS2 on the transcriptional activity of PR in a breast cancer cell line (T-47D-MTVL) harboring a PR-dependent luciferase reporter gene." (PMID 30813351, 2019). "SPF27 was initially identified as a cDNA amplified in human breast cancers (BCAS2), and is a unique protein domain of unknown function." (PMID 26130721, 2015). "Thus, we were interested in confirming whether BCAS2 could promote increased ERα transcriptional activity in breast cancer cells." (PMID 30813351, 2019). "Coimmunoprecipitation assays in both, transfected monkey kidney COS7 cells and breast cancer MCF7 cells, confirmed interaction between BCAS2 and ERα in the absence and presence of E2." (PMID 30813351, 2019). "Also, we unmasked the tumor-promoting function of BCAS2 in NSCLC, which was consistent with several previous studies in breast cancer, prostate cancer, and esophageal cancer." (PMID 34663267, 2021). "In order to determine the effect that BCAS2 may have on breast cancer development, we used MCF7 breast cancer cells to determine its effect on proliferation and clonogenicity." (PMID 30813351, 2019). "Luciferase reporter gene assays showed that overexpression of BCAS2 is able to enhance ERα transcriptional activity to an extent similar or greater than that found for the SRC-1 coactivator in ER positive (MCF7) or ER negative (MDA-MB-231) breast cancer cell lines in the presence of E2." (PMID 30813351, 2019).
esophageal cancer (4 papers, 2018 to 2023). A primary or metastatic malignant neoplasm involving the esophagus. "Conversely, miR-486 was found to suppress the growth and metastasis of esophageal cancer by targeting CDK4/BCAS2." (PMID 31976317, 2019).
prostate carcinoma (4 papers, 2020 to 2023). A carcinoma that arises from epithelial cells of the prostate gland. "Previous studies suggested that BCAS2 is involved in double-strand breaks (DSB); therefore, we aimed to characterise its mechanism and role in prostate cancer (PCa)." (PMID 32963349, 2020).
Alzheimer disease (3 papers, 2016 to 2022). A progressive, neurodegenerative disease characterized by loss of function and death of nerve cells in several areas of the brain leading to loss of cognitive function such as memory and language. "Thus, the impaired dendritic development in cKO mice further suggests that a lack of BCAS2 may cause neurodegenerative diseases, which supports previous reports of Alzheimer’s disease (AD) patients showing low mRNA expression of BCAS242." (PMID 27713508, 2016).
male infertility (3 papers, 2017 to 2025). The inability of the male to effect fertilization of an ovum after a specified period of unprotected intercourse. "Here, the authors find BCAS2 enriched in mice spermatogonia in the testes, and BCAS2 deletion in germ cells alters alternative splicing of spermatogenesis-related genes, causing male infertility." (PMID 28128212, 2017). "The heterozygotes not only showed male infertility, resembling the phenotype of Bcas2 germ cell-specific knockout mice reported previously, but also exhibited impaired definitive hematopoiesis, consistent with the earlier study." (PMID 40511787, 2025). "Prior work has shown BCAS2 to function as a post-transcriptional regulator of spermatocyte meiosis initiation such that the conditional knockout of BCAS2 in male germ cells results in impaired spermatogenesis and male infertility." (PMID 34041246, 2021). "Disruption of BCAS2 in germ cells with Vasa-Cre led to male infertility, but has little effect on spermatogonia." (PMID 28128212, 2017). "Using a conditional knockout mouse model, we demonstrated that specific deletion of Bcas2 in male germ cells leads to a failure of spermatogenesis and male infertility." (PMID 28128212, 2017). "This could be explained by male infertility as previously documented in Bcas2 knockout mice." (PMID 40511787, 2025).
breast tumors (2 papers, 2013 to 2023). "BCAS2 was first identified as a highly expressed oncogenic gene in breast tumors, and was later found to be the core component of CDC5L/Prp19 splicing complex, which mainly takes part in pre-mRNA splicing and DNA damage response." (PMID 37901468, 2023).
microcephaly (2 papers, 2016 to 2022). A congenital or acquired developmental disorder in which the circumference of the head is smaller than normal for the person's age and sex. "We found that BCAS2 upregulates β-catenin splicing, and BCAS2 conditional knockout (cKO) in the postnatal forebrain of animals caused microcephaly-like features, dendritic malformation, and poor learning and memory phenotypes due in part to downregulated β-catenin." (PMID 35410459, 2022). "It is worthwhile to investigate the volume of various regions in the forebrain (such as the cerebral cortex) and the progenitor proliferation of BCAS2 cKO to obtain more insight into the BCAS2-null-induced microcephaly." (PMID 27713508, 2016). "BCAS2 cKO mice showed a microcephaly-like phenotype with a reduced volume in the dentate gyrus (DG) and low levels of learning and memory, as evaluated using Morris water maze analysis and passive avoidance, respectively." (PMID 27713508, 2016). "Conditional knockout (cKO) of BCAS2 in the forebrain resulted in a microcephaly-like brain size." (PMID 27713508, 2016). "In terms of brain morphology, BCAS2 cKO mice exhibited a microcephaly-like phenotype." (PMID 27713508, 2016). "Hence, BCAS2 cKO in the forebrain resulted in a microcephaly-like phenotype." (PMID 27713508, 2016).
autism (1 paper, 2022). Persistent deficits in social interaction and communication and interaction as well as a markedly restricted repertoire of activity and interest as well as repetitive patterns of behavior. "In addition, genetic variants of the BCAS2 gene linkage region (1p13.2) were associated with the risk of autism, which implies that BCAS2 is associated with neural-related functions." (PMID 35410459, 2022).
benign prostate hyperplasia (1 paper, 2020). "To determine whether BCAS2 may serve as a marker of progression and prognosis of human PCa, we performed IHC to stain BCAS2 and β-catenin, which is a potential downstream target of BCAS2, in tissue microarrays that contained benign prostate hyperplasia and PCa tissues." (PMID 32963349, 2020).
cognitive deficits (1 paper, 2016). "Our data suggest that the BCAS2-null-induced small brain size may result from dendrite malformation, thus resulting in cognitive deficits." (PMID 27713508, 2016).
Infertility (1 paper, 2023). "Conditional disruption of BCAS2 in germ cells led to mouse infertility." (PMID 37248466, 2023). "In mouse oocytes, a lack of BCAS2 affected the function of RPA in DNA damage repair in mouse zygotes and resulted in infertility." (PMID 37248466, 2023).
cancer (9 papers, 2019 to 2025). A tumor composed of atypical neoplastic, often pleomorphic cells that invade other tissues. "Several studies have demonstrated the regulation of Bcas2 on AS in sperm cells, oocytes, pancreatic β cells and several types of cancer cells." (PMID 40585763, 2025). "BCAS2 is a pre-mRNA-splicing factor and was reported to play an important role in alternative mRNA splicing and development of oocyte, spermatogonia, and cancer cells, as well as DNA break repair." (PMID 38384303, 2024). "Combined with previous studies, these findings demonstrate that BCAS2 gene has potential physiopathologic and therapeutic implications in diseases or cancers related to male reproductive disorders." (PMID 37901468, 2023). "Additionally, the study of the BCAS2 gene in Hezuo pigs also provides a new avenue for veterinary scientists to further understand diseases or cancers related to reproductive disorders." (PMID 37901468, 2023). "Bcas2 has been acknowledged as an RBP that plays a role in AS during mitosis in highly proliferating cells such as sperm cells and cancer cells, with little information available on its function in B cells." (PMID 40585763, 2025). "However, the role that BCAS2 may play in cancer has been poorly elucidated." (PMID 30813351, 2019).
tumor (7 papers, 2018 to 2023). "Knockout of Bcas2 resulted in a significant decrease in the ratio of BrdU-positive cells in the human granulosa-like tumour (KGN) cell line." (PMID 37248466, 2023). "The possible synergistic effect of both mechanisms may explain the role of BCAS2 in promoting carcinogenesis and/or tumour progression." (PMID 32963349, 2020). "In addition, we propose that BCAS2 has a potential role in tumour progression based on the correlation of the expression levels of BCAS2 and its downstream effector β-catenin with clinical and pathological parameters." (PMID 32963349, 2020).
neurodegenerative disease (1 paper, 2016). A disorder of the central nervous system characterized by gradual and progressive loss of neural tissue and neurologic function. "Hence, BCAS2 may also be a therapeutic target for neurodegenerative diseases." (PMID 27713508, 2016).
BCAS2 also shares sentences with these, for which no sentence is quoted: colon cancer (1 paper); endometrial cancer (1); hepatocellular carcinoma (1); infection (1); influenza (1); non-small cell lung carcinoma (1); papillary thyroid carcinoma (1).